CGAS (cyclic GMP-AMP synthase)
Diseases named in the same sentence as CGAS in open-access papers (continued):
Sharing a sentence is not in itself a finding about the gene and the disease.
autoimmune disease (continued). "This review explores the mechanisms by which TCMs interact with the cGAS-STING pathway to regulate immunity, focusing on their roles in infectious diseases, malignancies, and autoimmune disorders." (PMID 39737190, 2024). "TTN regulates abnormal cGAS-STING signalling pathway activation by modulating the interaction between STING and IRF3, demonstrating significant therapeutic potential for autoimmune diseases and ALI mediated by the cGAS-STING pathway." (PMID 39148120, 2024). "The cGAS-STING pathway’s response to cytosolic DNA plays an important role in pathogen infections, autoimmune diseases, and anti-tumor immune responses." (PMID 38970078, 2024). "The cGAS–STING pathway represents a novel therapeutic target for preventing and treating various diseases, including cancer and infectious and autoimmune diseases." (PMID 39125448, 2024). "The cGAS-STING signaling pathway not only plays a crucial role in pathogen infections and autoimmune diseases but also significantly contributes to the occurrence and development of many aseptic inflammatory diseases." (PMID 39540037, 2024). "cGAS-STING signalling is involved in various diseases, such as cancer, autoimmune diseases, infections, inflammation and metabolic abnormalities." (PMID 39183465, 2024). "By targeting cGAS proteins, PAH reduces the interferon response, offering a potential therapeutic approach for cGAS-mediated autoimmune diseases." (PMID 39737190, 2024). "Moreover, the cGAS-STING pathway is involved in regulating the immune balance in the female reproductive system, and the aberrant activation of this pathway may lead to an attack by the immune system on normal tissues, which can cause autoimmune diseases." (PMID 39445027, 2024). "Altogether, our study provides a mechanistic rationale for autoimmune disease in DM2 by linking RNA repeat expansion with ER mitochondrial stress, cGAS activation and the induction of systemic autoinflammation and autoimmunity." (PMID 38378748, 2024). "In summary, various inhibitors of cGAS-STING ­regulate cell physiological effects based on different mechanisms, among which are effective in inhibiting inflammation, attenuating autoimmune diseases in animals." (PMID 39183465, 2024). "The cGAS(Cyclic GMP-AMP Synthase)-STING signaling pathway has emerged as a key mediator of inflammation during infection, tumors, inflammation, and autoimmune diseases." (PMID 37422464, 2023). "Innate immune DNA-sensing pathways, such as cGAS-STING, TLR9, and inflammasome, are well characterized as key regulators of antiviral host immune defense and autoimmune diseases." (PMID 37777633, 2023). "Inhibiting cGAS activity suppresses IFN-stimulated gene expression and ameliorates autoimmune diseases and sepsis." (PMID 37759732, 2023). "cGAS-STING is a component of innate immunity in humans, and its role in autoimmune diseases such as SS is extremely important." (PMID 37786436, 2023). "Inhibitors and activators of cGAS and STING are potential drugs for the treatment of several diseases, such as cancer and autoimmune disorders, respectively." (PMID 37354378, 2023). "More and more studies have found that the cGAS–STING pathway plays an important role in anti-infection, antitumor, and autoimmune diseases." (PMID 38251231, 2023). "The cGAS-STING pathway is involved in the development of infectious diseases, autoimmune diseases, and cancer." (PMID 35108342, 2022). "The TREX1 exonuclease degrades DNA to prevent aberrant nucleic-acid sensing through the cGAS-STING pathway, and dominant Aicardi–Goutières Syndrome type 1 (AGS1) represents one of numerous TREX1-related autoimmune diseases." (PMID 35885962, 2022). "In the past, many medicines have been proven to have inhibitory functions in the cGAS–STING pathway and have provided viable therapeutic methods for some diseases, such as autoimmune disease, pancreatitis and infectious disease." (PMID 36195926, 2022).
autoimmune disease (continued). "Third, accumulating data suggest that autoimmune diseases are closely related to the activation of the cGAS-STING pathway, and dry eye is a common complication of autoimmune diseases such as Sjogren’s syndrome." (PMID 35812407, 2022). "Excessive activation of cGAS-STING signaling by endogenous dsDNA is related to the development of inflammatory and autoimmune diseases, including systemic lupus erythematosus (SLE), Aicardi-Goutières syndrome (AGS), and neurodegenerative diseases." (PMID 35185917, 2022). "Disrupting one piece of these regulatory mechanisms leads to the imbalance of cGAS‒STING signaling that induces or aggregates multiple sterile inflammatory diseases, including autoimmune diseases, neurodegenerative diseases, metabolic disorders, and cancers." (PMID 35084490, 2022). "An increasing number of studies have revealed an important relationship between the cGAS-STING signaling pathway and autophagy, cellular senescence, antitumor immunity, inflammation, and autoimmune diseases." (PMID 35185917, 2022). "TREX1 prevents excessive accumulation of endogenous auto-DNA and prevents aberrant activation of DNA-mediated cGAS-STING signaling, while structurally inactivated TREX1 leads to the IFN-dependent autoimmune disease AGS." (PMID 36172373, 2022). "This procedure inhibits the cGAS–STING signalling pathway and markedly improves the progression of autoimmune disease." (PMID 36195926, 2022). "The cGAS–STING pathway is involved in the regulation of infectious diseases, anti-tumor immunity, and autoimmune diseases; in addition, it plays a key role in the development of central nervous system (CNS) diseases." (PMID 36618820, 2022). "As research progressed, researchers identified impressive expressions of the cGAS–STING pathway in cancer and autoimmune diseases as well." (PMID 34906241, 2021). "This article summarizes the current progress on cGAS-STING pathway modulators and lays the foundation for further investigating therapeutic development in autoimmune diseases and tumors." (PMID 34867409, 2021). "In recent years, rapid progress has been made in clarifying the structure and mechanism of key proteins in the cGAS-STING pathway and in revealing the important role of this pathway in human autoimmune disease and cancer." (PMID 34867409, 2021). "We anticipate that there will be more efficient and less toxic immune regulatory agents targeting cGAS-STING available in the future and applied for clinical practice to provide safer and more effective treatments for autoimmune disease and cancer." (PMID 34867409, 2021). "In hand with basic discovery, the role of cGAS-STING has been appreciated far beyond microbial recognition especially in pathological conditions such as cancer and autoimmune diseases." (PMID 34084165, 2021). "Furthermore, dysregulation of the cGAS‒STING pathway has been implicated in a spectrum of pathological conditions, but what is the connection between cGAS and/or STING dysregulation and metabolic dysfunction, cancer, autoimmune diseases, neurodegenerative disorders, and aging?" (PMID 34665236, 2021). "The central role of the cGAS-STING pathway in various human pathologies such as cancer, infections, autoimmune diseases, and inflammatory diseases has prompted the search for therapeutics targeting the cGAS-STING-TBK1 axis." (PMID 33708225, 2021). "The role of cGAS/STING signaling in immune and autoimmune diseases seems to be a major driver, and there is an increased interest in targeting this pathway." (PMID 34298904, 2021). "Activated cGAS instigates the signaling cascades to activate type I interferon (IFN) expression, critical for host defense and autoimmune diseases." (PMID 33105828, 2020). "Excessive host DNA activates the cGAS signaling pathway, leading to aberrant IFN activation and autoimmune diseases, such as systemic lupus erythematosus (SLE)." (PMID 33105828, 2020).
autoimmune disease (continued). "The effects of cGAS/STING in defenses against infection and autoimmune diseases have been well studied, still it is worthwhile to discuss the roles of cGAS/STING pathway beyond the “classical” realm of innate immunity." (PMID 35006429, 2020). "Abnormal activation of cGAS/STING pathway in inflammatory and autoimmune diseases is well discussed in other papers." (PMID 35006429, 2020). "Dysregulated activation of the cyclic GMP-AMP synthase-stimulator of interferon genes (cGAS-STING) pathway by self-DNA contributes to interferonopathy and promotes autoimmune diseases." (PMID 28771599, 2017). "The cGAS-STING signaling is recently established as instrumental for the onset and progression of autoimmune diseases." (PMID 28095500, 2017). "However, in autoimmune diseases such as AGS and SLE, TREX1 dysfunction leads to cytosolic DNA accumulation, resulting in persistent activation of the cGAS–STING pathway and excessive inflammatory responses in multi-organ." (PMID 40595456, 2025). "Investigating the interaction mechanism between the ubiquitination of the cGAS-STING pathway and the IRF3/IRF7 pathway may elucidate its significant involvement in autoimmune disorders and antiviral responses." (PMID 40028324, 2025). "Similarly, DNase II deficiency promotes lysosomal DNA stress, leading to activation of cytoplasmic double-stranded DNA sensors, such as cGAS-STING and AIM2, and thereby autoinflammatory and autoimmune diseases." (PMID 40037613, 2025). "STING agonists, including cGAMP analogs, show promise in cancer immunotherapy and as vaccine adjuvants, while small-molecule inhibitors of cGAS or STING, such as covalent STING inhibitors, demonstrate potential for treating autoimmune diseases (e.g., AGS) and other chronic inflammatory disorders." (PMID 40697819, 2025). "Thus, positive regulation of LLPS of cGAS-dsDNA can be used to activate antiviral and innate immunity, and negative regulation of LLPS of cGAS-dsDNA can be used to treat autoimmune diseases." (PMID 39757214, 2025). "These endogenous dsDNA could activate the cGAS/STING pathway, thereby enhancing the activity of antigen‐presenting cells and T cells, and contributing to antitumour immunity, autoimmune diseases and chronic inflammation." (PMID 40292672, 2025). "Given the potential role of the cGAS/STING pathway in autoimmune diseases, targeted therapy against this pathway may provide new strategies for the treatment of autoimmune diseases such as T1DM." (PMID 39365284, 2024). "CCDC50 downregulation enhances the immunological response mediated by cGAS-STING, which is induced by serum from SLE patients, implying that cGAS-STING maybe a possible target for autoimmune diseases." (PMID 39183465, 2024). "On this basis, our study reported that TTN can play an anti-inflammatory role by inhibiting the cGAS-STING pathway and also provided a new idea for the treatment of autoimmune diseases and ALI by tanshinone capsule, which is conducive to its wider clinical application." (PMID 39148120, 2024). "Furthermore, autoimmune disorders can be suppressed by anti‐inflammatory bioactive lipids such as lipoxin A4 (LXA4), through inhibition of the cGAS‐STING pathway." (PMID 38500390, 2024). "The cGAS-STING signaling pathway serves as a crucial cytoplasmic DNA-sensing pathway, playing a pivotal role in regulating immune responses to cancer, infections, and autoimmune diseases by triggering the production of IFN-1 which modulates immune regulation." (PMID 39061208, 2024). "We will also focus on the important roles of cGAS–STING signal under pathological conditions, such as infections, cancers, autoimmune diseases, neurological diseases, and visceral inflammations, and review the progress in drug development targeting cGAS–STING signaling pathway." (PMID 38525112, 2024). "However, as a key inducer of IFN-I responses, cGAS-STING also promotes stage-specific tumor initiation and proliferation, and mediates the pathogenesis of autoimmune diseases." (PMID 38999073, 2024).
autoimmune disease (continued). "The omnipresence of the cGAS-STING pathway in vivo indicates that its overactivation could lead to undesired inflammatory responses and autoimmune diseases, which underscores the necessity of developing both agonists and inhibitors of the cGAS-STING pathway." (PMID 38999073, 2024). "Therefore, the cGAS-MITA/STING pathway is a potential target for intervention in infectious, inflammatory and autoimmune diseases as well as cancer." (PMID 37932533, 2023). "The cGAS/STING pathway is an important signaling pathway involved in the immune response, and excessive pathway activation can lead to inflammation or the development of autoimmune diseases." (PMID 38124089, 2023). "In recent years, an increasing number of studies have shown a strong link between abnormal activation of the cGAS-STING signaling pathway, a natural immune pathway mediated by the nucleic acid receptor cGAS, and the development and progression of autoimmune diseases." (PMID 38066431, 2023). "Glab is a specific inhibitor of the cGAS-STING signaling pathway and may be used in the clinical therapy of cGAS-STING pathway-mediated autoimmune diseases." (PMID 38066431, 2023). "Thus, the CGAS-STING pathway is not only important in host defense, but has a critical role in sepsis and autoimmune diseases." (PMID 37759732, 2023). "Given the role of cGAS-STING in intrinsic immunity, the search for a compound that can effectively inhibit the over-activation of this pathway is considered a promising intervention strategy for the treatment of autoimmune diseases." (PMID 38066431, 2023). "The cGAS-STING signaling pathway is an important process in cytoplasmic DNA sensing, and has critical roles in regulating pathogen infection, tumor immunity, and autoimmune diseases." (PMID 35889509, 2022). "Our results suggest that targeting cGAS-STING, a pathway for which agents are presently being developed to treat autoimmune diseases and cancer, may prove to be a viable treatment option for patients with SSc." (PMID 36400785, 2022). "The cGAS-STING signaling pathway may be a promising drug target for inflammatory and autoimmune diseases or inform the design of effective nucleic acid drugs to treat various diseases." (PMID 35185917, 2022). "The cGAS-STING signaling pathway is an important cytoplasmic DNA-sensing pathway in vivo, which takes part in regulating pathogen infection, cancer immune response, and autoimmune diseases by triggering the production of type I IFN." (PMID 35889509, 2022). "Suppression of BAF1 increases the accumulation of cGAS within discrete intranuclear foci and induces a robust IFN response, which may be involved in the pathogenesis of autoimmune diseases." (PMID 35084490, 2022). "However, cGAS-STING–induced inflammation is a troublesome problem that cannot be ignored; it has a tight connection with autoimmune diseases, neurodegeneration disease, and metabolic disorders." (PMID 36591232, 2022). "Consequently, the regulation of the cGAS-STING pathway and the expression of type I IFN and related inflammatory factors are of great significance for alleviating autoimmune diseases and intervening in the progression of malignant tumors." (PMID 36231006, 2022). "So far, the most promising cGAS inhibitor came from synthesized AMD derivative X6, which could attenuate the autoimmune disease phenotype in Trex1−/− mice." (PMID 33968056, 2021). "Collectively, our study reveals that PAH can effectively inhibit cGAS-STING signaling and could be developed toward the treatment of cGAS-mediated autoimmune diseases." (PMID 33968056, 2021). "Therefore, the role of cGAS-STING in auto-inflammatory and autoimmune diseases has been established leading to a chronic activation of the IFN pathway, which can be detrimental." (PMID 33708225, 2021).
autoimmune disease (continued). "Therefore, cGAS-STING is now considered as an attractive target to identify novel biomarkers and design therapeutics for auto-inflammatory and autoimmune disorders as well as infectious diseases and cancer." (PMID 33708225, 2021). "In the absence of SAMHD1, constitutive activation of the cGAS/STING pathway ensues, providing an explanation as to why mutations in this locus is linked to the development of various cancers and the autoimmune disease Aicardi-Goutières Syndrome." (PMID 33563288, 2021). "The growing interest in the cGAS/STING pathway is such that several molecules and strategies to target this route are already delineated and evaluated in preclinical models and in clinical trials for autoimmune diseases." (PMID 35008251, 2021). "Perturbation of the cGAS-STING pathway in HSPCs may be involved in the pathogenesis of hematopoietic disorders, autoimmune diseases, and inflammation-related diseases and may be candidate therapeutic targets." (PMID 33329537, 2020). "Therefore, the cGAS-MITA pathway must be tightly controlled to ensure proper immune response against pathogens and to avoid autoimmune diseases." (PMID 29546673, 2018). "However, when these nucleases are impaired or nuclear or mtDNA leak into the cytoplasm, cGAS—which lacks the ability to distinguish self from non-self DNA— can become activated, contributing to inflammatory and autoimmune diseases." (PMID 40697819, 2025). "cGAS (cyclic GMP-AMP synthase)-STING (stimulator of interferon genes) signaling plays a vital role in innate immunity, while its deregulation may lead to a wide variety of autoinflammatory and autoimmune diseases." (PMID 39965124, 2025). "Hyperactivity of cGAS-STING pathway may lead to sustained immune response and result in autoimmune diseases, such as systemic lupus erythematosus, Aicardi-Goutières syndrome, STING-associated vasculopathy with onset in infancy, rheumatoid arthritis and psoriasis." (PMID 38515746, 2024). "For example, in autoimmune diseases such as systemic lupus erythematosus and Aicardi-Goutieres syndrome (AGS), patients produce a large amount of their own DNA antibodies, leading to the activation of the cGAS-STING signaling pathway and triggering an inflammatory response." (PMID 39540037, 2024). "In various autoimmune diseases, dysfunctional TREX1 (Three prime Repair Exonuclease 1) leads to accumulation of endogenous single-stranded DNA (ssDNA), double-stranded DNA (dsDNA) and DNA/RNA hybrids in the cytoplasm and triggers immune activation through the cGAS–STING pathway." (PMID 37870446, 2023). "Nevertheless, we anticipate that the development of drugs targeting the cGAS–STING pathway and their translation into clinical applications in the near future will help further ameliorate the condition of patients with cancer, inflammation, and autoimmune diseases." (PMID 37686127, 2023). "Meanwhile, the tested results in other signaling pathways showed that compound 2 was a selective inhibitor of cGAS and reduced the mRNA level of IFN-β in bone marrow derived macrophages (BMDM) of AGS model TREX1-/- mice, thus indicating the potential for the treatment of autoimmune diseases." (PMID 36172373, 2022). "There were five clusters: cGAS-STING pathway in inflammation and tumor immunology (red), cGAS-STING pathway sensing virus and its structure foundation (green), cGAS-STING pathway in innate immunity (purple), in ROS-induced inflammasome activation (yellow), and in autoimmune disease (blue)." (PMID 35720348, 2022). "These fundamental findings suggested that cGAS hampers the unusual noncanonical inflammasome activation through other DNA sensors, which could be a new targeted therapy for treating autoimmune disease." (PMID 36591278, 2022). "In addition, targeted approaches are being developed based on the modulators of the cGAS-STING pathway such as the immunosuppressor MYSM1, which may be considered as a therapeutic target for inflammatory and autoimmune diseases." (PMID 33708225, 2021).